CCR10 (C-C motif chemokine receptor 10)
Diseases named in the same sentence as CCR10 in open-access papers (continued):
Sharing a sentence is not in itself a finding about the gene and the disease.
cutaneous melanoma (2 papers, 2014 to 2016). A primary melanoma arising from atypical melanocytes in the skin. "In contrast, it was observed that overexpression of CCR10 and CCR7 resulted in severe outcome of human cutaneous melanoma growth, as determined by high risk of relapse and death of patients." (PMID 27807435, 2016).
Hepatitis (2 papers, 2016 to 2018). Inflammation of the liver. "Having established that CCR10 is significantly upregulated in short-term murine models of hepatitis, we next investigated CCR10′s role in long-term DEN-induced murine hepatocarcinogenesis using CCR10 KO and WT mice." (PMID 29445190, 2018). "In earlier reports, CCR10-expressing CD25+CD4+FOXP3+ Treg cells were identified to be critical for maintaining the potent anti-inflammatory properties in liver inflammation." (PMID 27716621, 2016). "Thus, we investigated CCR10′s effects upon hepatocellular apoptosis as well as compensatory hepatocellular proliferation in the DEN-treated murine model of hepatitis." (PMID 29445190, 2018). "Both hepatitis models displayed significantly upregulated hepatocellular TNF and CCR10 protein expression." (PMID 29445190, 2018).
lung adenocarcinoma (2 papers, 2016 to 2024). A carcinoma that arises from the lung and is characterized by the presence of malignant glandular epithelial cells. "Thus, we examined the expression of CCR3/CCR10 on various tumor stromal cells, revealing widespread expression of CCR3 on endothelial cells, cancer-associated fibroblasts, and pericytes in lung adenocarcinoma." (PMID 39075504, 2024). "We analyzed adjacent sections of paraffin embedded lung adenocarcinoma samples (n = 27) by immunohistochemistry with antibodies against CD34, CCR3 and CCR10." (PMID 27250766, 2016). "Taken together, the evidences indicated that CCR3, but not CCR10, was the main receptor of CCL28 on the microvascular endothelial cells, especially in lung adenocarcinoma." (PMID 27250766, 2016).
lung carcinoma (2 papers, 2022 to 2023). "In our study, the survival of advanced lung cancer treated with immunotherapy was significantly reduced in those patients with high baseline levels of CCR9+ or CCR10+ CD4+ T cells, or CXCR4+ CD8+ T cells." (PMID 35740564, 2022). "The result suggested that the CCR10 protein level in lung cancer tissue was not affected by Pc infection, or Gem treatment or the combination of both." (PMID 37916167, 2023).
lymphopenia (2 papers, 2020 to 2021). Reduction in the number of lymphocytes. "This diminution is likely due to residual lymphopenia, but it cannot be ruled out that these cells expressing CCR10 could also be still present in tissues instead of recirculating in the periphery in convalescent individuals." (PMID 35069575, 2021).
skin inflammation (2 papers, 2021 to 2025). "For example, CCR10/CCL27 interactions were proven to alleviate skin inflammation via regulating T cells." (PMID 34831296, 2021). "The CCR10/CCL27 interaction mediates the recruitment of memory T cells to the skin and regulates the induction of antigen-specific skin inflammation in vivo." (PMID 40040698, 2025).
abortion (1 paper, 2019). the ending of pregnancy by removing a fetus or embryo before it can survive outside the uterus. "CCL28 has been found to induce apoptosis in decidual stromal cells, and a higher expression of the receptors of CCL28 (CCR3, CCR10), in these cell populations in spontaneous abortion is displayed prior to a pro-inflammatory stimulation." (PMID 30755659, 2019).
Acinetobacter infection (1 paper, 2024). "A reduction of neutrophil accumulation was also observed in the BAL and lung of Ccl28−/− mice during Acinetobacter infection, with neutrophils recruited to the lung harboring surface CCR3 and CCR10." (PMID 39193987, 2024).
acute GVHD (1 paper, 2024). "In pediatric patients with skin acute GVHD, the proportion of CCR10+ CD4+ subgroups in peripheral blood T cells is significantly higher than in non-GVHD patients, and this subgroup vanishes after the resolution of acute GVHD." (PMID 39840040, 2024).
airway hyperresponsiveness (1 paper, 2015). "The Protein Epitope Mimetic CCR10 antagonist, POL7085, significantly and dose-dependently decreased allergen-induced airway hyperresponsiveness and airway inflammation after once daily local treatment." (PMID 26112287, 2015).
allergic rhinitis (1 paper, 2025). Inflammation of the nasal mucous membranes caused by an IgE-mediated response to external allergens. "In allergic rhinitis, allergen exposure boosted CCR10 (NALT) and epithelial CCL28 with CCR10 memory CD4 T-cell infiltration." (PMID 41050670, 2025).
Candida infection (1 paper, 2012). "Of the chemoattractant mediators, several chemokines (Ccl25, Ccl27, Ccl28) and chemokine receptors (Ccr9, Ccr10, Cxcr5, Cxcr6, Cxcr7) associated with adaptive immunity were not induced after Candida infection." (PMID 22916017, 2012).
chronic allograft nephropathy (1 paper, 2018). "Of further interest, CCR 10, the receptor for CCL27 ligand, is expressed by the podocytes and thus a role for CCL27 in podocytes function and injury in chronic allograft nephropathy is a potential hypothesis for future studies." (PMID 30214382, 2018).
colitis (1 paper, 2024). Inflammation of the colon. "Based on these findings and our observations of CCL28-dependent neutrophil accumulation in the gut during STm colitis and in the lung during Ab infection, we performed flow cytometry on single-cell suspensions from infected mouse tissues to evaluate surface expression of CCR3 and CCR10." (PMID 39193987, 2024).
Crohn disease (1 paper, 2016). A gastrointestinal disorder characterized by chronic inflammation involving all layers of the intestinal wall, noncaseating granulomas affecting the intestinal wall and regional lymph nodes, and transmural fibrosis. "Further, treatment of Crohn’s disease patients resulted in reduced expression of CCR10 corroborated with reduced inflammation in those patients [reviewed in Ref." (PMID 27807435, 2016).
diabetes (1 paper, 2017). "The decrease in the numbers of DETCs upon diabetes induction is most likely explained by homeostasis, rather than egression, given that diabetic and control mice expressed comparable levels of αE, integrin β4 and CCR10." (PMID 28729536, 2017).
E. coli infection (1 paper, 2016). "Taken together, the upregulated expression of CCL28 and CCR10 in the intestinal mucosa following consumption of high-dose BLS-mix is partly involved in clearance of the pathogen, but also is associated with intestinal inflammation during E. coli infection." (PMID 27424033, 2016).
Hypertension (1 paper, 2023). The presence of chronic increased pressure in the systemic arterial system. "A decrease in the CCR10+ Treg subpopulation with increased immunosuppressive function has been shown in patients with hypertension." (PMID 37504566, 2023).
infectious colitis (1 paper, 2024). A viral or bacterial infectious process affecting the large intestine. "The reciprocal regulation of CXCR2 and CCR3/CCR10 in neutrophils and each receptor’s contribution to neutrophil migration and retention during infectious colitis requires further study." (PMID 39193987, 2024).
infectious mononucleosis (1 paper, 2014). A condition characterized by an increase in mononuclear white blood cells and swollen lymph nodes, which is usually caused by infection with the Epstein-Barr virus. "Neither the CXCR4 nor the CCR10 markers conform with the phenotypic relationship with LCL cells and with EBV positive B cells localized at the periphery of tonsil in infectious mononucleosis." (PMID 25162594, 2014).
influenza (1 paper, 2025). An acute viral infection of the respiratory tract, occurring in isolated cases, in epidemics, or in pandemics; it is caused by serologically different strains of viruses (influenzaviruses) designated A, B, and C, has a 3-day incubation period, and usually lasts for 3 to 10 days. "Both CCL27 and CCL28 have also been shown to provide immunity against influenza and HIV due to the fact that adjuvant activity is dependent on CCR10-expressing plasma B cells that produce IgA and accumulate at mucosal surfaces." (PMID 40975172, 2025).
lichen sclerosus (1 paper, 2025). "Blocking the CCR10/CCL27 interaction could represent a potential strategy to prevent inflammatory processes in lichen sclerosus." (PMID 41301909, 2025).
liver cancer (1 paper, 2023). An epithelial or non-epithelial malignant neoplasm that arises from the liver. "Then we asked whether CCR10 mediated this pathway as demonstrated in our previous study of a liver cancer model infected with Py." (PMID 37916167, 2023).
multiple sclerosis (1 paper, 2016). A progressive autoimmune disorder affecting the central nervous system resulting in demyelination. "It is observed that drugs used to treat multiple sclerosis such as glatiramer acetate, dimethyl fumarate, and monomethyl fumarate upregulate the expression of chemokines receptor 10 (CCR10) on the surface of human IL-2-activated NK cells." (PMID 27807435, 2016).
non-small cell lung carcinoma (1 paper, 2025). A group of at least three distinct histological types of lung cancer, including non-small cell squamous cell carcinoma, adenocarcinoma, and large cell carcinoma. "Chemokine receptors such as CCR9 and CCR10 have also been identified as potential biomarkers in non-small cell lung cancer (NSCLC)." (PMID 41149503, 2025).
Obesity (1 paper, 2023). Accumulation of substantial excess body fat. "Furthermore, topical application of myristoylated CCR10 binding domain 7 amino acid (Myr-CBD7) peptide prevented CCR10-eNOS interaction and subsequent eNOS downregulation, enhanced eNOS/NO levels, and improved wound healing in obesity-induced diabetic mice." (PMID 36713846, 2023). "Here we demonstrate that neutralization of excessive CCL28 not only reduced inflammation but also CCR10-eNOS interaction in diabetic wounds, thereby enhancing eNOS/NO level, VEGF production, microvessel density, and wound healing in the obesity-induced mouse model of type 2 diabetes." (PMID 36713846, 2023).
osteosarcoma (1 paper, 2008). A usually aggressive malignant bone-forming mesenchymal neoplasm, predominantly affecting adolescents and young adults. "In a recent retrospective osteosarcoma patient study, the mRNA expression of the receptors CXCR4, CCR7 and CCR10 by osteosarcoma tissue was linked to clinical outcome." (PMID 18215331, 2008).
polyposis (1 paper, 2024). "Our analysis revealed distinct patterns: XCR1, CXCL13, and CXCR6 expression levels were diminished in M1-staged and advanced CRC cases, while CXCR6 expression was elevated in CRC patients with a history of polyposis, and CCR10 expression was heightened in lympho-invasive CRC." (PMID 39835121, 2024).
Respiratory tract infection (1 paper, 2015). An infection of the upper or lower respiratory tract. "During respiratory tract infections, in addition to its chemokine role in attracting immune cells expressing CCR10, CCL28 likely provides additional mucosal immunity by exerting an antimicrobial effect against pathogens." (PMID 26112287, 2015).
Salmonella Infections (1 paper, 2024). Infections with bacteria of the genus SALMONELLA. "CCL28 stimulation of bone marrow neutrophils in vitro increased their antimicrobial activity and ROS production during Salmonella infection, which was reverted by blocking CCR3 but not CCR10." (PMID 39193987, 2024).
sarcopenia (1 paper, 2024). Progressive decline in muscle mass due to aging which results in decreased functional capacity of muscles. "CCR10/CTACK interaction may relate to the development of sarcopenia due to their crucial roles in regulating multiple immune cells with conflicting effects, including helper T cells, cytotoxic T cells, regulatory T cells, natural killer cells, myeloid‐derived suppressor cells and so on." (PMID 38556722, 2024).
skin infection (1 paper, 2025). An inflammatory process affecting the skin, caused by bacteria, viruses, parasites, or fungi. "In CD8 T cells, CCR10 proved important for priming and memory formation after skin infection, particularly for tissue memory resident T cells (TRM) development and survival; CCR10 expression peaked during the effector phase of skin infection and declined after 30 days." (PMID 41050670, 2025).
skin tumors (1 paper, 2016). "Human keratinocyte-derived skin tumors can evade T cells antitumor activity by downregulating the expression of CCR10." (PMID 27807435, 2016).
Stroke (1 paper, 2022). Sudden impairment of blood flow to a part of the brain due to occlusion or rupture of an artery to the brain. "A panel of genes encoding chemokine receptors, including Ccr10, Cxcr6, and Cxcr3, was upregulated in circulating CD8+ TRLs after stroke." (PMID 35912857, 2022).
T-cell lymphoma (1 paper, 2022). "Expression of receptor CCR3 or CCR10 is elevated in the inflammatory process and T-cell lymphoma." (PMID 36016177, 2022).
type 1 diabetes (1 paper, 2014). "On day 8, both 1,25(OH)2D3 and TX527 had induced CCR10 on CD4+ and CD8+ T cells, not only from control donors, but also from patients with type 1 diabetes." (PMID 25279717, 2014).
viral infections (1 paper, 2015). "We thereby suggest that a study of the role of a CCR10 antagonist such as POL7085 in the CCL28-driven lung T cell recruitment during viral infections in mice would be useful." (PMID 26112287, 2015).
tumor (82 papers, 2008 to 2025). "CCR10 also participates in tumor-associated lymph angiogenesis." (PMID 41050670, 2025). "Ligand-receptor interaction networks revealed significant enrichment of the CCL28-CCR10 axis in high-TMs groups, which recruits CCR10+ Tregs to tumor nests, forming local immunosuppressive microenvironments." (PMID 40630945, 2025). "Glioblastoma overexpresses CCR10, with CCR10-CCL27-p-Akt signaling driving proliferation and invasion, blocking CCR10 or p-Akt reduces tumor growth." (PMID 41050670, 2025). "Tumor-derived CCL28 recruits CCR10 Treg cells in ovarian cancer, promoting angiogenesis and immune tolerance under hypoxia." (PMID 41050670, 2025). "Emerging synthetic biology strategies such as CCR10 knock-down or overexpression, or engineering CAR T cells with CCR10-based trafficking modules offer innovative avenues to modulate immune responses and restrict tumor spread." (PMID 41050670, 2025). "The hypoxic tumour microenvironment upregulates the expression of CCL28 in many tumours and thereby promotes the infiltration of CCR10 expressing Treg cells, which secrete vascular endothelial growth factor A (VEGF-A) and promote angiogenesis and metastasis." (PMID 40852716, 2025). "Although CCR10 is typically expressed on immune cells, it has also been detected at elevated levels in various tumor cells, including malignant melanoma and squamous cell carcinoma, where its overexpression is linked to poor prognosis." (PMID 40597436, 2025). "The multifaceted roles of CCR10 in immune regulation and tumor biology underscore its importance in both homeostasis and disease contexts." (PMID 41050670, 2025). "Hypoxia can amplify the expression of CCL28, attracting CCR10-positive Treg cells into the tumor, suppressing the Teffs function, and also elevating the levels of VEGFA in the TME." (PMID 38500876, 2024). "For example, targeting CCR10 or CCR5 with receptor-blocking monoclonal antibodies significantly delayed tumor growth in mouse models." (PMID 38500876, 2024). "It has been documented that CCR10 interacts with CCL28 to promote plasma cell metastasis into the tumor stroma." (PMID 39835121, 2024). "This heightened expression of CCL28 in hypoxic conditions fosters the attraction of CCR10-expressing Treg cells to the tumor site, thereby facilitating tumor tolerance and angiogenesis." (PMID 39000453, 2024). "CCL28 released by hypoxic tumor cells recruits CCR10+ Tregs, promoting tumor progression and angiogenesis." (PMID 39000453, 2024). "Treg cells highly express certain chemokine receptors (CCR4, CCR5, CCR8, CCR10), which facilitates their preferential migration to the tumor microenvironment." (PMID 38500876, 2024). "Studies have shown that Tregs express a variety of chemokine receptors, such as CCR4, CCR5, CCR8 and CCR10, which can respond to a variety of chemokines released during tumor growth, and then participate in the migration of Tregs to tumor tissues." (PMID 37950246, 2023). "The correlation between CCR10 and lymph node metastasis was demonstrated in B16 F1 cells, where CCR10 overexpression induced an immunosuppressive environment, leading to tumour growth and lymph node metastasis." (PMID 37170733, 2023). "For example, tumor VEGF-D synthesis upregulates C-C motif chemokine receptor type 10 (CCR10) expression and increases LEC migration towards tumor-derived chemokine ligands 27 and 28 (CCL27/28)." (PMID 38201272, 2023). "PI also inhibits tumor angiogenesis through multiple pathways and targets, as well as inhibiting the epithelial-mesenchymal transition (EMT) of tumor cells by suppressing the CCR10-mediated PI3K/Akt/GSK-3β/Snail signaling pathway." (PMID 36429033, 2022). "Hypoxia-induced C-C motif chemokine ligand 28 (CCL28) promotes tumor immune evasion by attracting C-C motif chemokine receptor 10 (CCR10)-positive Tregs to the tumor site." (PMID 36072596, 2022).